CXCR2 (C-X-C motif chemokine receptor 2)
Diseases named in the same sentence as CXCR2 in open-access papers (continued):
Sharing a sentence is not in itself a finding about the gene and the disease.
tumor (continued). "Therefore, treatment of Ptenpc−/−; Trp53pc−/− tumor-bearing mice with a CXCR2 inhibitor promotes TAMs re-education, leading to tumor inhibition." (PMID 37055829, 2023). "The analysis of tumour volumes showed that anti-CXCR2 antibody inhibited tumour growth." (PMID 37037815, 2023). "Tumor-secreted oxysterols recruit CXCR2+ neutrophils that can release tumor growth factors." (PMID 36479100, 2022). "Chemokine receptors CXCR1/CXCR2 and their ligands (CXCL1-3, 5, 8) have been associated with tumor associated neutrophil (TAN) and/or polymorphonuclear–MDSC (PMN-MDSC) infiltration in various tumors, including BCa, and targeted in patients with breast cancer and prostate cancer." (PMID 36613562, 2022). "It is possible that CXCR2's role in tumor suppression varies depending on the stage of the tumor." (PMID 36164329, 2022). "As expected, blockade of either CSF1R (in CAFs), or MIP2 (in CAFs), or CXCR2 (in macrophages) enhanced the IL-12/IL-10 expression ratio in the latter, which was further corroborated with enhanced cytotoxicity against tumor cells." (PMID 35315360, 2022). "Therefore, the CXCR2-mediated infiltration and the formation of tumor-aiding NETs by the TANs in a location-dependent manner can be reversed by inhibition of NETs." (PMID 35158784, 2022). "For instance, IL-8 binding to the cognate receptors, namely CXCR1 and CXCR2, may promote a dysfunctional inflammatory microenvironment that contributes to tumor progression." (PMID 35954247, 2022). "Therefore, targeting CCL2/CCR2 and CXCLs/CXCR2 can potentially regulate immune cell infiltration in the tumor microenvironment and improve the therapeutic effect of HCC." (PMID 36403057, 2022). "CXCL7 and its receptor CXCR1/CXCR2, which are aberrantly expressed in tumors, may represent new targets for clinical tumor immunotherapy." (PMID 35837284, 2022). "Based on the significant association between the two chemokine axes and HCC, we hypothesized that targeted therapies against CCL2/CCR2 and CXCLs/CXCR2 can improve the anti-tumor effect of TACE." (PMID 36403057, 2022). "This may reflect that CAFs induce tumor infiltration by CXCR2-expressing MDSCs, which argues for multi-pronged therapy." (PMID 36143975, 2022). "Based on the existing evidence, we hypothesized that blocking the CCL2/CCR2 and CXCLs/CXCR2 axes would enhance the TACE-induced inhibition of tumor growth." (PMID 36403057, 2022). "A second retrospective cohort of synchronously resected primary tumours and matched liver metastases was assessed via immunohistochemistry (IHC) for protein expression of the CXCL8 receptor CXCR2 to determine any association with clinicopathological features in the metastatic setting." (PMID 35879507, 2022). "In addition, SX-682 (a small-molecule inhibitor of CXCR1 and CXCR2) can also inhibit the migration of MDSCs and eliminate the accumulation of MDSCs in tumor." (PMID 36225938, 2022). "Identifying and elucidating the mechanism by which blocking CXCR2 may affect tumor growth is of particular interest." (PMID 36060811, 2022). "CXCR2 was also reported to be associated with EMT and resistance of tumor cells to chemotherapy." (PMID 35963638, 2022). "In addition, tumor-derived oxysterols have been reported to recruit pro-tumor neutrophils in a manner dependent on C-X-C motif chemokine receptor 2, which in turn suppresses anti-tumor immune responses and supports tumor growth." (PMID 36269001, 2022). "CXCR2 is also significant in the recruitment of different cells to the tumor niche." (PMID 35216283, 2022). "Thus, we assumed that CXCR2 is involved in aggressive behaviors of tumor cells mediated by PDCD10 in PAs." (PMID 35963638, 2022). "Therefore, clearly, blocking CXCR2 in neutrophils has a significant effect on the BrM tumor behavior." (PMID 35158784, 2022). "Similarly, CXCR2 is expressed at a low level in tumor tissues, and the prognosis of CXCR2 with low expression is worse." (PMID 36401283, 2022).
tumor (continued). "Thus, by targeting CXCR2, we can simultaneously inhibit multiple features of cancers, including stem cell/proliferation/invasion/migration of tumour cells, angiogenesis, fibrosis, a feature of cancers with poor prognosis, and immune tolerance." (PMID 36497191, 2022). "Tumor-produced CXCR2 agonists were also involved in the modification of neutrophil function." (PMID 36555469, 2022). "Similarly, the combination of PD-1 antibody with CSF-1R inhibitor and selective CXCR2 inhibitor significantly reduce tumor growth compared with PD-1 antibody alone." (PMID 35672862, 2022). "CXCR2, the CXC receptor expressed by neutrophils, can bind with its ligand chemokine family (CXCL1, CXCL2, CXCL3, CXCL5, CXCL7, and CXCL8) to recruit neutrophils to the TME and participate in the mobilization of tumour-associated neutrophils." (PMID 36743929, 2022). "CXCL2 has also been demonstrated to recruit MDSCs and promote tumor growth in breast cancer, pancreatic ductal adenocarcinoma, oral cancer, and glioblastoma, whereas knockdown of CXCR2 in MDSCs and knockdown of CCL2 reduced the recruitment of MDSCs to tumor sites in mice." (PMID 35854339, 2022). "CXCR2 plays a role in tumor progression by promoting the migration of MDSCs into the TME." (PMID 35924159, 2022). "In addition to promoting angiogenesis, the CXCL8/CXCR2 axis also exerts multiple effects on proliferation, invasion, and migration of tumor cells." (PMID 35898871, 2022). "Overexpression of CXCR1 and CXCR2 strengthened the invasion capability of tumor cells." (PMID 35571062, 2022). "Thus, tumour infiltration of CXCR2-expressing neutrophils is characteristic of both murine models and human NASH-HCC and associates with resistance to anti-PD1 therapy in experimental models of NASH-HCC." (PMID 35477863, 2022). "Moreover, tumor-derived oxysterols recruit TANs which is dependent on the CXCR2 pathway, thereby facilitating tumor growth by promoting angiogenesis and immunosuppression." (PMID 35585567, 2022). "Since WT macrophages stimulated with IL4 showed an increased level of Cxcr2 transcripts, it was determined whether increased levels of CXCR2 induced by IL4 mediate the IL4-dependent increased transendothelial migration of tumor cells." (PMID 36077870, 2022). "Moreover, in HCC patient tissue, CD66b+ neutrophils and CXCR2+ cells predominantly localised to NASH-HCC tumours with expression of the two markers correlating, and furthermore being demonstrated to be colocalised at the cellular level." (PMID 35477863, 2022). "Inhibitors of CXCL5 or its receptor CXCR2 could be potentially applied in clinic in different mechanisms, such as regulating the tumor immune microenvironment, reducing angiogenesis and progression, improving treatment utility by combination therapy." (PMID 35150082, 2022). "Therefore, to evaluate the CXCR2 expression, neutrophils were incubated in respective tumor conditioned media (TCM) and qRT-PCR was performed." (PMID 35158784, 2022). "With the aim to overcome the deleterious effects of neutrophils in cancer, the IL-8 and CXCR1/CXCR2 inhibition could reduce neutrophils migration to the tumor, thus avoiding NETs formation and eventually preventing drug resistance." (PMID 36591453, 2022). "However, combined CCR2 and CXCR2 blockade led to a sustained inhibition of systemic mobilization of both CCR2+ TAMs and CXCR2+ neutrophils, which enabled anti-tumor immune response and potentiated FOLFIRINOX chemotherapy." (PMID 35740692, 2022). "In addition, the expression levels of Ki-67, which represents a level of tumor proliferation, together with CXCR2 were decreased in the PDCD10-shRNA group." (PMID 35963638, 2022). "Moreover, the combination of CXCL5 and CXCR2 elevates programmed death-ligand 1 (PD-L1) expression in mouse tumor cells, depending on the activation of PI3K/AKT signaling." (PMID 35935996, 2022).
tumor (continued). "IL-8 participates in infection response and the pathogenesis of cancers by interacting with specific cell surface G protein–coupled receptors CXCR1 and CXCR2, which leads to the recruitment of neutrophils, stimulation of angiogenesis and stimulation of tumor cell proliferation." (PMID 35493517, 2022). "In addition, CXCR1 and CXCR2 play an important role in the release of NETs by TANs, which in turn shield tumor cells from CD8 T cell and NK cell cytotoxicity." (PMID 35158948, 2022). "Additionally, the CXCR2 antagonist SCH‐527123 not only inhibited tumor proliferation, invasion, and angiogenesis, but also enhanced the sensitivity of CRC to oxaliplatin treatment." (PMID 35702353, 2022). "Among the canonical effects caused by tumor-derived IL-8, VEGF-independent angiogenesis is one of most characterized; by binding CXCR1 and CXCR2 expressed by endothelial cells, soluble IL-8 induces endothelial cell proliferation and capillary tube organization." (PMID 36289899, 2022). "Therefore, to unequivocally evaluate the specific contribution of CXCR2 signaling in macrophages during tumor cell transendothelial migration, we isolated BMDMs from Cxcr2−/− mice and compared them to WT BMDMs in the eTEM assay." (PMID 36077870, 2022). "In contrast, CXCR2 deletion reduced tumor angiogenesis and enhanced tumor necrosis." (PMID 35791509, 2022). "In addition, overexpression of CXCL8 and CXCR1 or CXCR2 led to tumor cell growth and metastasis via activating PI3K/AKT and ERK1/2 MAPK signaling." (PMID 36612163, 2022). "In an experiment using KPC mice, one group firstly received the CXCR2 inhibitor AZ13381758 100 mg/kg BID for 2 weeks to increase T cell infiltration into the tumor, followed by the administration of anti-PD-1 antibodies (10 mg/kg BIW) while AZ13381758 continued." (PMID 35139879, 2022). "To date, CXCR2 has been extensively studied in various types of neoplasms." (PMID 35963638, 2022). "In addition, CXCR2 and CXCR4, which are associated with pro-tumor in ICIs, were shown to be lower in PTPRD/PTPRT mutant cancers compared with WT (both P < 0.01)." (PMID 36248841, 2022). "Notably, ligands (Cxcl1, Cxcl2, Cxcl3, Cxcl5) for the chemokine receptor CXCR2, the latter identified as being predominantly expressed by Ly6G+ neutrophils, were all increased in tumour tissue." (PMID 35477863, 2022). "In addition, activation of the CXCL1/CXCR2 signaling axis was also observed to promote tumor angiogenesis and progressive growth by activating STAT3 and enhancing VEGF levels." (PMID 36612163, 2022). "However, CXCR2 has also been found on epithelial cells, endothelial cells, some neuroendocrine cells (e.g., pituitary), and various tumor cells." (PMID 35963638, 2022). "Similar tumor-promoting effects were also found in the CXCL3/CXCR2 axis." (PMID 36612163, 2022). "Therefore, the interaction between CXCR2 and tumor microenvironment results of critical importance for tumor progression." (PMID 34012923, 2021). "Therefore, selective inhibition of CXCR2 shows promising prospect in improvement of current anti-tumor therapy." (PMID 33814009, 2021). "Since CXCR2 may also stimulate tumor endothelial cells, we measured the expression of intratumoral CD31 and found no changes upon the therapy, indicating the absence of effect on tumor vascularization." (PMID 33578808, 2021). "Blockade of CXCLs/CXCR2 using selective CXCR2 inhibitor SB225002 could effectively decrease the infiltration of neutrophils in tumor microenvironment." (PMID 33814009, 2021). "The area under the ROC curve for CXCL8 was higher than those for CXCR2 and classical tumor markers." (PMID 34680333, 2021). "Classically, CXCR2 is expressed on leukocytes, endothelial cells and tumor cells." (PMID 34124076, 2021). "In addition to IL-8, migration inhibitory factor (MIF) from tumor cells induces CXCR2-dependent chemotaxis, improved neutrophil survival, and release of CCL4 and MMP-9, helping develop aggressive HNSCC phenotype." (PMID 33925575, 2021).
tumor (continued). "Moreover, CXCR2 acts as an autocrine or paracrine growth factor to induce tumor invasion and migration." (PMID 34692853, 2021). "It is worth mentioning that CXCR2 inhibitors showed a better response to rCXCL1 on CAF than tumor CM, suggesting that LAMC1 may also influence other factors contributing to the formation of iCAF." (PMID 34218518, 2021). "Blocking CXCR2 in early-stage disease may prevent the recruitment of anti-tumor neutrophils, but the effect of CXCR2 inhibition on TAN phenotypes necessitates further study and may vary depending upon the proportion of N1 versus N2 TANs in the TME." (PMID 34944914, 2021). "Expression of CXCL1 also recruits T-regs to the tumor microenvironment through CXCR2 signaling." (PMID 34298673, 2021). "Interestingly, both Mon_1 and Mon_3 also expressed the matrix metalloproteinase inhibitor TIMP1 and CXCL5 (the ligand for CXCR2) that promote recruitment of suppressive granulocytes and enhance tumor growth in mice." (PMID 34921160, 2021). "CD8+ T-cell activation in response to PD-1 blockade induced a PD-L1/NLRP3 inflammasome signaling cascade that ultimately led to the recruitment of CXCR2+PMN-MDSCs into tumor tissues through HSP70/TLR4/Wnt5a/CXCL5 signaling axis, thereby dampening the resulting antitumor immune response." (PMID 35003065, 2021). "IL-8 produces an effect upon binding to its receptors, CXC chemokine receptors 1 and 2 (CXCR1 and CXCR2), which are heterodimeric receptors primarily expressed on immune cells such as neutrophils, but may also be present on the surface of various tumor cells." (PMID 34066014, 2021). "NPV values for CXCL8 and CXCR2 were higher in comparison to those of classical tumor markers." (PMID 34680333, 2021). "However, obese CXCR2 cKO mice had a greater OC-induced ascites accumulation, showing reduced ascitic floating tumor cells and tumor-attached Mo/Mφ with lower triglyceride, free fatty acid, CCL2, and TNF levels compared to obese WT mice." (PMID 34638514, 2021). "Overall, our data show that Cxcr2 ablation accelerates primary tumor growth in the mammary gland." (PMID 34070438, 2021). "Thus far, the effect of the IL8/CXCR2 pathway on human tumor cells was studied in vitro and immunodeficient rodent models." (PMID 33807899, 2021). "Our study has proven that the inhibition of CXCR2 pathway may not only lead to OC antitumor properties but may also act as a chemosensitizer of tumor cells to cisplatin." (PMID 34038868, 2021). "Although CXCR2 blockade inhibits recruitment of granulocytic myeloid cells to the tumor, it may also inhibit NK recruitment." (PMID 33953710, 2021). "CXCR1 and CXCR2 constitute the primary mechanism for the recruitment of neutrophils and MDSCs, which could enhance tumor progression and suppress immune therapy efficacy." (PMID 35011369, 2021). "Blockage of CXCR2 may enhance the sensitivity and effectiveness of immunotherapy and suppress tumor progression." (PMID 34840630, 2021). "CXCR1 and CXCR2 are receptors for IL-8 (CXCL8), an inhibitory chemokine involved in recruitment of tumor-associated neutrophils or myeloid derived suppressor cells (MDSCs), tumor proliferation and angiogenesis." (PMID 33746981, 2021). "In contrast, PAI-1 increased the production of CXCL5, suggesting that PAI-1 might increase the tumor infiltrating CXCR2+ myeloid-derived suppressor cells (MDSCs) and tumor-associated neutrophils (TANs), both of which are known to be immunosuppressive cells." (PMID 34912726, 2021). "Meanwhile, CXCLs/CXCR2 axis is thought to have close relationship with tumor drug-resistance." (PMID 33814009, 2021). "Interleukin and chemokine receptors IL4R and CXCR2—pivotal molecules in alternative macrophage activation and immunosuppression—show significantly higher expression in the NE-low tumor phenotype compared to NE-high (8.71 ± 2.16 vs. 7.88± 1.84, p = 0.009 and 5.5 ± 1.02 vs. 3.83 ± 2.11, p < 0.001)." (PMID 34200100, 2021).
tumor (continued). "CXCR2, binding to its ligands, is important in tumorigenesis and tumor progression." (PMID 34124076, 2021). "Though CXCR2 on tumor cells was up-regulated followed DDP treated, blockade of CXCR2 couldn’t alter the expression of those immunosuppressive markers." (PMID 33814009, 2021). "We further found expression level of CXCR2 on tPBN surface was much higher than that on nPBN surface, which might lead to enhanced chemotaxis of neutrophils in tumor." (PMID 33814009, 2021). "Recently, studies have shown that the CXCL1/CXCR2 signaling pathway could regulate the inflammatory response and promote tumor cell proliferation, invasion, and transvascular metastasis, acting as essential molecules in the progression of inflammation." (PMID 34306038, 2021). "We next investigated lung metastasis in twelve−week−old animals and observed the appearance of a higher number of metastases in PyMT−Cxcr2−/− compared to PyMT WT animals, demonstrating that Cxcr2 knock−down affects not only primary tumor growth and spleen size, but also distant metastasis." (PMID 34070438, 2021). "These correlation results suggested that the tumor and ascites burdens may be critical for the survival of CXCR2 WT and cKO mice, respectively." (PMID 34638514, 2021). "Moreover, tumors with molecular apocrine phenotype, i.e., expressing both AR and FOXA1 biomarkers, exhibited significantly lower density of intra-tumor CD11b- or CXCR2-positive cells (p = 0.001 and p = 0.006, respectively)." (PMID 34066060, 2021). "This may be achieved by inhibition of CXCR2 or IL-17 to reduce neutrophil migration into the tumor, or by anti-TGF-β that leads to a shift from N2 to the N1 phenotype of neutrophils with subsequent acquisition of antitumor activity." (PMID 34831167, 2021). "In mouse models of PDAC, depletion of neutrophils using anti-Ly6G antibodies or inhibition of CXCR2 signaling results in reduced tumor growth, abrogation of metastasis, and improved influx of cytotoxic T cells, which enables an improved checkpoint inhibition therapy response." (PMID 34099731, 2021). "Furthermore, studies on rhabdomyosarcoma in mice have shown that disruption of CXCR2-dependent MDSC trafficking to the tumor resulted in significantly increased antitumor effects." (PMID 33917501, 2021). "In addition, combining CSF1R inhibitors with a CXCR2 antagonist blocked the infiltration of these cells and showed strong anti-tumor effect." (PMID 33842370, 2021). "Likewise, CXCL8/CXCR1 and CXCL8/CXCR2 axis are known to induce tumor growth, angiogenesis, motility, and EMT." (PMID 33925575, 2021). "Tumor‐secreted CXCL1 remodeled the formation of iCAF through CXCR2/pSTAT3." (PMID 34218518, 2021). "ELR+ CXCLs, including CXCL1-3, CXCL5-8, and CXCL17, bind to CXC chemokine receptor 2 (CXCR2) to promote endothelial cell survival and tumor angiogenesis, whereas most ELR− CXCLs, including CXCL4, CXCL9-11, and CXCL16, bind to CXCR3 to inhibit endothelial cell proliferation and angiogenesis." (PMID 34085699, 2021). "For instance, CXCR2 expression, which promotes myeloid cell recruitment, was associated with poor outcome when tumor edges were examined, but not when central tumor areas were examined." (PMID 33372414, 2021). "Interestingly, the knock-down of Cxcr2 in PyMT animals led to an increased growth of the primary tumor and lung metastasis." (PMID 34070438, 2021). "The same group, applying a similar experimental microfluidic approach, found that MDA-MB-231 extravasation was mediated by C-X-C Motif Chemokine Receptor 2 (CXCR2) in tumour cells and the chemokine CXCL5 secreted by the bone mimicking environment, as CXCR2 blocking decreased extravasation." (PMID 34572836, 2021). "In the inflammatory tumor microenvironment, macrophages, myeloid derived suppressor cells (MDSC), endothelial cells and stromal fibroblasts secrete CXCL1, which activates the NF-kB pathway in CXCR2+BC cells and promotes tumor growth, while contributing to local immunosuppression." (PMID 34195201, 2021).